ENSG00000267022 (novel protein)
Gene: Protein-coding gene on chromosome 19 (44,025,354 to 44,087,318, forward strand). Ensembl gene ENSG00000267022.
Genetic constraint (gnomAD): Missense variants: 558 observed, 661.97 expected, observed/expected ratio (o/e) 0.84, 90% interval 0.79 to 0.9. Synonymous variants: 186 observed, 229.35 expected, observed/expected ratio (o/e) 0.81, 90% interval 0.72 to 0.92.